UBA5 (ubiquitin like modifier activating enzyme 5)
Diseases named in the same sentence as UBA5 in open-access papers (continued):
Sharing a sentence is not in itself a finding about the gene and the disease.
Becker muscular dystrophy (1 paper, 2022). Becker muscular dystrophy (BMD) is a neuromuscular disease characterized by progressive muscle wasting and weakness due to degeneration of skeletal, smooth and cardiac muscle. "Furthermore, the expression of UFC1 is also up-regulated in skeletal myocytes differentiated from induced pluripotent stem cells derived from familial ALS (C9ORF72 mutations), and the expression of UBA5, the E1 ligase for UFMylation has recently been associated with Becker muscular dystrophy." (PMID 36472367, 2022).
cervical squamous cell carcinoma (1 paper, 2021). A squamous cell carcinoma arising from the cervical epithelium. "UBA5 was upregulated in several tumor types, including breast invasive carcinoma (BRCA), cervical squamous cell carcinoma (CESC), and colon adenocarcinoma (COAD)." (PMID 34572561, 2021).
Infantile encephalopathy (1 paper, 2018). Encephalopathy with onset in the infantile period. "Similar to our previous work on UBA5-related severe infantile encephalopathy, we show that mutations in UFM1 itself as well as in UFC1, encoding the sole E2 conjugating enzyme for UFM lead to widespread impairment of ufmylation." (PMID 29868776, 2018).
leukemia (1 paper, 2019). A malignant (clonal) hematologic disorder, involving hematopoietic stem cells and characterized by the presence of primitive or atypical myeloid or lymphoid cells in the bone marrow and the blood. "The E1-like ubiquitin-activating enzymes (e.g., UBA5) have been recently described as important targets for future treatment of cancer progression, such as leukemia, among others." (PMID 31597257, 2019).
lung carcinoma (1 paper, 2022). "Meanwhile, one of the UBA5 inhibitors derived from adenosine 5′sulfamate (ADS) was demonstrated to reduce the proliferation of lung cancer cells, highlighting the possible implications of the UBA5 inhibitor for cancer therapy." (PMID 35884562, 2022).
Obesity (1 paper, 2024). Accumulation of substantial excess body fat. "As expected, the expression levels of hepatic Uba5, Ufc1, Ufl1, and Ufm1 are significantly reduced in patients with obesity, MASLD, and MASH by analyzing the public data sets." (PMID 39858578, 2024).
ovarian serous cystadenocarcinoma (1 paper, 2021). A malignant serous cystic epithelial neoplasm arising from the ovary. "However, in other tumors, such as ovarian serous cystadenocarcinoma (OV), UBA5 was more highly expressed in normal samples than in tumor samples." (PMID 34572561, 2021).
status epilepticus (1 paper, 2021). Status epilepticus is defined as a continuous seizure lasting more than 30 min, or two or more seizures without full recovery of consciousness between any of them. "Second, the patient with the most severe UBA5 genotype was also the patient who presented with the most severe phenotype, dying of complications of status epilepticus in the first weeks of life." (PMID 33811063, 2021).
cancer (7 papers, 2019 to 2025). A tumor composed of atypical neoplastic, often pleomorphic cells that invade other tissues. "In vitro data showed that this inhibitor of UBA5 selectively hindered the proliferation of cancer cells, particularly effective at concentrations above 50μM in cells with elevated levels of UBA5." (PMID 39247188, 2024). "The mRNA expression levels of UBA5 in different types of cancer was obtained from the GEPIA and UALCAN databases." (PMID 34572561, 2021). "Although UBA5 is a promising target for cancer treatment, only two UBA5 inhibitors have been reported in the literature." (PMID 34572561, 2021). "In this study, we utilized the GEPIA and UALCAN databases to determine the expression of UBA5 in various cancers." (PMID 34572561, 2021). "Amplification, deletion or mutation of genes encoding the UFMylation factors (UBA5, UFC1, UFL1, UfSP2 and UFM1) has been detected in malignant tumors from various tissues and organs in the TCGA database, indicating that UFMylation may promote or suppress tumorigenesis in different cellular contexts." (PMID 30783677, 2019). "Furthermore, the results showed that overexpression of UBA5 reduced the autophagic flux in MDA-MB-231 cancer cells, which could be reversed by usenamine A. Through our research, we shed new light into the development of UBA5 inhibitors and their application in cancer treatment." (PMID 34572561, 2021). "Since UBA5 is very important for the UFM1 protein conjugation in erythroid development and for promoting proliferation and survival of cancer cells, this enzyme is considered as a therapeutic target for disrupting cancer progression." (PMID 31597257, 2019).
tumor (4 papers, 2015 to 2023). "Recent reports indicate that the inhibition of ubiquitin-like modifier-activating enzyme 5 (UBA5) can impede tumor development." (PMID 34572561, 2021). "Whereas depletion of ASC1, UBA5, or both prevent colony formation and tumor growth, overexpression of ASC1 markedly increases them." (PMID 25852645, 2015).
neurologic disease (2 papers, 2016 to 2023). "To date, 24 variants in UBA5 have been reported to cause neurological disease." (PMID 38046095, 2023). "A role for UBA5 in human neurological disease has yet to be identified." (PMID 26872069, 2016). "However, a crucial role for UBA5 in human neurological disease remains to be reported." (PMID 26872069, 2016).
infection (1 paper, 2011). The state of being infected such as from the introduction of a foreign agent such as serum, vaccine, antigenic substance or organism. "Therefore, we investigated the effects of active site mutations in the Uba5, the Ufm1 activating enzyme, on parasite growth in human macrophage infection experiments." (PMID 21264253, 2011).
UBA5 also shares sentences with these, for which no sentence is quoted: Intellectual disability (4 papers); early-onset epileptic encephalopathy (2); movement disorder (2); Seizure (2); atherosclerosis (1); autosomal recessive cerebellar ataxia (1); cerebellar ataxia (1); Cerebellar atrophy (1); colon adenocarcinoma (1); diabetes (1); Epileptic spasm (1); Failure to thrive (1); Hip dysplasia (1); infantile epileptic encephalopathy (1); ischemic heart diseases (1); schizophrenia (1); Skeletal muscle atrophy (1); West syndrome (1).